LMO2 (LIM domain only 2)
Description:
Acts with TAL1/SCL to regulate red blood cell development. Also acts with LDB1 to maintain erythroid precursors in an immature state.
Synonyms: LMO-2; RBTN2; RBTNL1; RHOM2; TTG2
Tractability: PROTAC: ubiquitination databases record sites on it.
Target class: Transcription factor
Gene: Protein-coding gene on chromosome 11 (33,858,574 to 33,892,076, reverse strand). Ensembl gene ENSG00000135363.
Subcellular location: Nucleus
Subcellular location (Human Protein Atlas): Nucleoplasm
Pathways (Reactome):
Gene expression (Transcription): RUNX1 regulates transcription of genes involved in differentiation of HSCs
Gene Ontology:
Molecular function: bHLH transcription factor binding; protein binding; RNA polymerase II-specific DNA-binding transcription factor binding; transcription coactivator activity; transcription coregulator binding
Biological process: positive regulation of transcription by RNA polymerase II; embryonic hemopoiesis
Cellular component: transcription regulator complex; nucleoplasm; nucleus
Genetic constraint (gnomAD): Loss-of-function variants: 14 observed, 19.57 expected, observed/expected ratio (o/e) 0.72, 90% interval 0.47 to 1.12. The upper end of that interval is the gene's LOEUF score, 1.12, which puts it in group 4 of 6, group 1 being the genes least tolerant of losing a copy. Missense variants: 266 observed, 277.09 expected, observed/expected ratio (o/e) 0.96, 90% interval 0.87 to 1.06. Synonymous variants: 123 observed, 109.42 expected, observed/expected ratio (o/e) 1.12, 90% interval 0.97 to 1.31.
Homologues: Orthologues: pig LMO2 (98% identical), guinea pig LMO2 (97% identical), macaque LMO2 (96% identical), dog LMO2 (95% identical), chimpanzee LMO2 (94% identical), mouse Lmo2 (94% identical), rat Lmo2 (94% identical), rabbit LMO2 (68% identical), tropical clawed frog lmo2 (67% identical), zebrafish lmo2 (63% identical). Paralogues in human: LMO3 (28% identical), LMO1 (28% identical), LMO4 (27% identical), LHX9 (26% identical), LHX2 (25% identical), LHX6 (25% identical), LHX8 (24% identical), LMX1B (24% identical), ZFHX2 (23% identical), LHX3 (22% identical), LMX1A (22% identical), ZFHX3 (21% identical), and 8 more.
Diseases named in the same sentence as LMO2 in open-access papers:
LMO2 is named in the same sentence as 63 diseases in open-access papers, as found by Europe PMC text mining. Sharing a sentence is not in itself a finding about the gene and the disease. The quoted sentences say what the papers report.
leukemia (56 papers, 2009 to 2025). A malignant (clonal) hematologic disorder, involving hematopoietic stem cells and characterized by the presence of primitive or atypical myeloid or lymphoid cells in the bone marrow and the blood. "In both of these cases, the leukemia was induced by an unintended activation of LMO2 when the retroviral vector inserted itself at or near the LMO2 gene, which has been linked to leukemia." (PMID 40364236, 2025). "These form a ternary complex with LMO2 and E3 ligase in leukaemia cells that induces degradation of LMO2 and is also accompanied by loss of associated bHLH proteins." (PMID 41385269, 2025). "Tragically, X-linked severe combined immune deficiency (X-SCID) gene therapy trials inadvertently caused leukemia in some patients due to activation of the LMO2 oncogene." (PMID 38836106, 2024). "For example, the formation of the LIM domain only 2 (LMO2) oncogene expression enhancer caused by insertion mutation transforms somatic cells into primary leukemia cancer cells." (PMID 36310856, 2022). "Here the authors, analysing enhancer-targeting sequence data, show that small insertions in transcriptional enhancers are frequently found near oncogenes, and demonstrate how one mutation deregulates expression of LMO2 in leukemia cells." (PMID 28181482, 2017). "The leukemia was caused due to the GRV provirus integration near proto-oncogenes including LIM Domain Only 2 (Rhombotin-Like 1)." (PMID 28536375, 2016). "We next explored potential roles for Lmo2 in controlling proliferation of MLL-ENL transduced cells as well as their ability to cause leukaemia following transplantation into irradiated recipients." (PMID 23708655, 2013). "The leukemia cells of these patients showed aberrant and high expressions of proto-oncogenes such as LMO2, which were caused by RV insertions within or near these loci." (PMID 23990961, 2013). "Similarly, we found a regulatory region bound by LMO2 upstream the Flt3l locus associated with differential opening of chromatin in Lmo2Tg DN3a thymocytes at all stages of leukemia development." (PMID 39849166, 2025). "Leukemias and clonal dominance in both animal models and human gene therapy clinical trials have been previously linked to insertional activation of LMO2, the MDS1/EVI1 gene complex, HOXB4, and a number of other transcription factor genes, but not previously to activation of an anti-apoptotic gene." (PMID 23118966, 2012). "The highly concordant nature of the genetic events giving rise to mouse and human leukemias with mutations at Lmo2 are an encouraging sign to those wanting to use mice to model human cancer and may help in designing safer methods for retroviral gene therapy." (PMID 19461887, 2009). "In these murine models, aberrant expression of LMO2 initiates leukemia by reprogramming a fraction of T-cell progenitors into preLSCs many months before the development of overt T-ALL." (PMID 39849166, 2025). "We next utilized scRNA-seq to uncover transcriptional heterogeneity among the L-IC-containing DN3 population within the context of Tal1/Lmo2-induced primary mouse leukemias, T-ALL#1 and T-ALL#2." (PMID 38553571, 2024). "As in most cases of vector-induced T-ALL, leukemia development was initiated by a single γ-RV insertion that occurred upstream to the LMO2 proto-oncogene leading to its dysregulation." (PMID 38688902, 2024). "We treated 6-week WT or leukemia-prone Tal1, Lmo2, and Tal1/Lmo2 mice expressing the reporter with doxycycline for 6 weeks to induce H2B-GFP expression." (PMID 38553571, 2024). "For example, in a trial for X-linked severe combined immunodeficiency, gene therapy inadvertently activated the LMO2 proto-oncogene, leading to leukemia in some patients." (PMID 38836106, 2024). "Further, LMO2 is frequently overexpressed in TAL1 expressing leukemias but in LMO2 transgenic mice TAL1 is dispensable for leukemogenesis." (PMID 35514954, 2022).
leukemia (continued). "In contrast, deletion of Lyl1 significantly increases leukemia latency in LMO2 transgenic mice suggesting that LYL1 supports transformation." (PMID 35514954, 2022). "In a subset of pediatric (3.7%) and adult (5.5%) T-ALL the LMO2 gene contains intronic indels that result in de novo binding sites for the leukemia-associated transcription factors MYB, ETS1 or RUNX1 and thus dysregulated LMO2 expression." (PMID 35514954, 2022). "Expression of Lmo2 accelerates the onset of leukemia in Tal1 transgenic mice, and LMO1/LMO2 are commonly expressed in human TAL1-driven T-ALL." (PMID 34501239, 2021). "Precisely, while pre-LSC self-renewal activity required continuous Lmo2 expression, overt leukemia frequently evolves in a Lmo2-independent manner." (PMID 34771671, 2021). "Further investigation revealed integration of the therapeutic gene into the LMO2 proto-oncogene locus, presumably resulting in the development of leukemia." (PMID 32850447, 2020). "The LMO2 (LIM Domain Only 2) protein has a crucial role in hematopoietic development and is associated with leukemia." (PMID 31959221, 2020). "These T-ALLs cluster with TAL1/LMO2-rearranged mature leukemias based on their gene expression signature." (PMID 30304769, 2018). "In contrast to Sca1‐Lmo2 T‐ALL, Lmo2 was expressed in Sca1‐Lmo2 + nu/nu leukemia and expression array data showed enrichment in human early T‐cell precursor (ETP) ALL genes, in agreement with human ETP ALL cases that commonly showed LMO2/LYL1 deregulation." (PMID 29880602, 2018). "Further study of one insertion, somatically acquired in primary leukaemia tumour genomes, reveals that it nucleates formation of an active enhancer that drives expression of the LMO2 oncogene." (PMID 28181482, 2017). "Unfortunately, some patients developed leukemia as a result of a γRV vector integration near or in the LIM domain only 2 (LMO2) oncogene that activated LMO2 expression." (PMID 27792127, 2016). "The proto-oncogene LIM-domain only 2 (lmo2) was traditionally considered to be a pivotal transcriptional regulator in hematopoiesis and leukemia." (PMID 27779255, 2016). "A critical function of LMO2 in T cell tumourigenesis is thus to form leukaemia-initiating cells (LICs) as a pool for further oncogenic mutations (discussed in §9)." (PMID 26108219, 2015). "Most intriguingly, this insertion occurred in a pediatric SCID-X1 patient who developed a leukaemia secondary to retroviral reinsertion (in front of LMO2, a known TAL1-cooperating oncogene) following gene therapy." (PMID 25615415, 2015). "By analogy with the transgenic mouse data, this cell will acquire self-renewal properties due to LMO2 expression and propagate to gradually produce a pool of cells within which the secondary mutations (such as NOTCH1) occur to give rise to frank leukaemia." (PMID 26108219, 2015). "It is likely that LMO2 and its protein partners in normal HSPCs also associate in T-ALL because many of them are co-expressed in the leukemias." (PMID 24465765, 2014). "In this study, c-Myc abrogation depleted leukemia LICs and prolonged survival in a Notch1 mutant Tal1/Lmo2 T-ALL mouse model." (PMID 25072021, 2014). "This idea is mechanistically similar to the HOXA-mediated activation of LMO2 in leukemias other than T-ALL." (PMID 24465765, 2014). "Several oncogenes, including LMO2, have very recently been reported to be target genes for vector integration in two patients that developed leukemia following retroviral-mediated gene therapy." (PMID 19725963, 2009). "Among the five leukemias that have occurred (four in the French and one in the UK trial), four had insertional mutations at LIM domain Only 2 (LMO2)." (PMID 19461887, 2009). "We have attempted to estimate the number of cells that carried an integrated vector in the HIR near exon 1 of the LMO2 locus in the leukemia patients who participated in the gene therapy trials for treatment of X-SCID." (PMID 19725963, 2009).
leukemia (continued). "Our high throughput insertion site analysis identified additional disease-related genes that are likely to cooperate with Lmo2 in leukemia induction." (PMID 19461887, 2009). "At the end of the pulse-chase period, a subset of Tal1 or Tal1/Lmo2 mice developed leukemia." (PMID 38553571, 2024). "Finally, CD53 is overexpressed in Lmo2 mouse leukemias and was shown to protect human TAL1+ JURKAT cells from apoptosis." (PMID 38553571, 2024). "LDB1 could promote leukemia development by regulating LMO2 expression, and forming the LDB1/LMO2 protein complex in AML." (PMID 37573405, 2023). "Furthermore, LDB1 is a necessary partner of LMO2, especially when it comes to the T-ALL mouse model, confirming that Ldb1 plays a role in Lmo2-induced leukemia." (PMID 37573405, 2023). "Despite the great excitement due to successful defective Moloney γRV-based correction of SCID-X1 in children, a major setback was encountered as the therapeutic gene was inserted into the LMO2 proto-oncogene region of the genome leading to leukemia development in a few patients." (PMID 36992407, 2023). "Although the retrovirus-based treatment of children with X-linked severe combined immunodeficiency (SCID-X1) was successful, the insertion of the therapeutic gene into the LMO2 proto-oncogene region of the genome led to the development of leukemia in a few patients." (PMID 36992407, 2023). "Microarray analysis revealed that LMO2 expressing thymocytes have higher Lyl1 expression compared to wild type thymocytes indicating a potential feed-forward mechanism reminiscent of the mechanism seen in TAL1 expressing leukemias." (PMID 35514954, 2022). "However, another study showed that KDM3B was located at the promoter area of the lmo2 gene and drove the occurrence of leukemia." (PMID 34490047, 2021). "For human leukaemias, it is difficult to ascertain whether the transforming action of Lmo2 is within HSCs or at some later lineage-committed stage of development." (PMID 32213936, 2020). "This is because there is preservation of the action of Lmo2 that leads to programming of the malignant cell fate in the stem cells that maintain the leukaemia, their immediate progeny and the partially differentiated leukaemia cells that are the bulk of a patient’s leukaemia cells." (PMID 32213936, 2020). "In addition, these leukemias showed enrichment in pluripotency, stemness, underscoring a reprogramming effect of Lmo2 in HSC/PC." (PMID 29880602, 2018). "This was demonstrated in early retroviral HSC IL2RG gene therapy for X-SCID patients, in which 4 of the 10 treated patients eventually developed leukemia, likely due to LMO2 activation induced by integration of the retrovirus and cooperation between the functions of LMO2 and IL2RG67." (PMID 29615705, 2018). "The ability of retroviral vector integration to initiate clonal expansion resulting in patient leukaemias with insertions at a subset of integration hotspots (LMO2, BMI1, CCND2) in gene therapy trials indicates the translational relevance of these observations." (PMID 27097319, 2016). "In order to test whether JQ1 interferes with leukemia initiation and reduces LICs, Tal1/Lmo2 mouse T-ALLs were transplanted into syngeneic recipients and vehicle or JQ1 administered for 3 weeks." (PMID 25072021, 2014). "In addition, we examined the cancer-related genes located within 30 kb of the FV and RV integration sites because all the RV insertion sites in gene therapy-related leukemia were shown within gene or within 30 kb of TSS of LMO-2 or BMI1." (PMID 23990961, 2013). "The role of LMO2 in oncogenesis was also demonstrated in two separate gene therapy trials for X-linked SCID, which were halted when five (out of 19) patients developed leukaemia." (PMID 20573277, 2010).
leukemia (continued). "On the other hand, results showing retroviral integration sites 35 kb upstream and 10.6 kb downstream of the TSS were reported in the patients, and sites 36.3 kb, 69.2 kb, 68.0 kb, 68.3 kb and 0.9 kb upstream of the LMO2 TSS were detected in a murine leukemia model." (PMID 19725963, 2009). "LMO2 is a T-cell oncogene, suggesting that these leukemias resulted from insertional mutagenesis." (PMID 19461887, 2009). "Thus, 2 of the AKXD murine leukemias with insertions at Lmo2 also contain insertions at Il2rg, a highly significant result (p = 1.34×10−9, see Text S1 for calculation)." (PMID 19461887, 2009). "Here, we show that the genes and signaling pathways deregulated in murine leukemias with retroviral insertions at Lmo2 are similar to those deregulated in human leukemias with high LMO2 expression and are highly predictive of the leukemias induced in SCID-X1 patients." (PMID 19461887, 2009). "To identify genes that might cooperate with Lmo2 in tumor induction we adapted an LM-PCR method to amplify the other viral insertions present in the five AKXD leukemias." (PMID 19461887, 2009). "Thus, we investigated whether ectopic expression of gp130 promotes LMO2-driven STAT3 activity in TF-1 leukemia cells, which highly express other complex proteins except for gp130." (PMID 35805116, 2022). "Taken together, therefore, the data presented here suggest that potential roles for LMO2 in leukaemia may extend beyond its traditional function as a T-ALL oncogene, and at least in some patients involve activation of an early developmental HOX-LMO2 regulatory hierarchy." (PMID 23708655, 2013). "Our data show that Lmo2 and Il2rg cooperate but may not be sufficient for leukemia development and additional mutations contribute to leukemia development." (PMID 19461887, 2009). "Consequently, these results suggest that vector integration at -1798 within the HIR may increase transcriptional activity of the LMO2 gene, similar to the report for vector integration at -2965 in the leukemia patient." (PMID 19725963, 2009). "In AML1-ETO leukemia, genomic data have suggested a functional complex among RUNX1, LDB1/LMO2, and HEB." (PMID 39450904, 2025). "Genes that are overexpressed in both MPAL subtypes blast cells compared to other leukemias and healthy controls include CD81, and LMO2." (PMID 37845689, 2023). "While the occurrence of GPR56, CD53 and CD59a on leukemia cells is known, GPR56, CD53 and CD59a are highly expressed in the thymocytes of Lck-Lmo2 mice relative to wild type thymocytes and are also on the overt human tumors in addition to CD7." (PMID 30962539, 2019). "We found that the majority of the TFs in the extracted rule have reported cell-type or tissue-specific expression specificities, such as IRF in lymphoblastoid cell-line, AP-1 in cervical cancer, HNF4 in liver and colon cells, LMO2 and GATA in leukaemia cells." (PMID 29363433, 2018). "Aberrant expression of LMO2, following activation by retroviral insertion, has also led to a T-ALL-like leukaemia arising in four of the children treated in X chromosome-linked severe combined immuno-deficiency syndrome (X-SCID) gene therapy trials." (PMID 26108219, 2015). "An example is LMO2 and IL2RG cooperation in leukemia cases among X-SCID patients where insertional mutagenesis of LMO2 results in an increased growth advantage in the presence of IL2RG." (PMID 24886479, 2014). "Given the importance of both LMO2 and HOX genes in acute leukaemias, we further demonstrated that the regulatory hierarchy of HOX control of LMO2 is activated in leukaemia mouse models as well as in patient samples." (PMID 23708655, 2013). "The transcription factor complex of AML1-ETO fusion protein, consisting of AML1-ETO, LMO2, LDB1 and LYL1, has recently been considered the key to leukemia maintenance and differentiation blocking, because knockout of this complex can delay leukemogenesis in mice." (PMID 37573405, 2023).